SV2C (synaptic vesicle glycoprotein 2C)
Description:
Plays a role in the control of regulated secretion in neural and endocrine cells, enhancing selectively low-frequency neurotransmission. Positively regulates vesicle fusion by maintaining the readily releasable pool of secretory vesicles. (Microbial infection) Receptor for C.botulinum neurotoxin type A (BoNT/A, botA); the toxin probably binds via extracellular loop 4. Recognition by BoNT/A relies on both protein-protein and protein-N-glycosylation; glycosylation of Asn-559 increases its affinity for BoNT/A. Also serves as a receptor for the closely related C.botulinum neurotoxin type A2; glycosylation is not essential but enhances the interaction. (Microbial infection) Possible receptor for C.botulinum neurotoxin type D (BoNT/D, botD); note that type D does not usually infect humans.
Synonyms: SLC22B3
Tractability: Small molecule: a drug acting on it is in phase 2 or 3 trials; a structure with a bound ligand is known; it belongs to a druggable protein family. Antibody: its Gene Ontology location is reachable by antibodies, with high confidence; UniProt predicts a signal peptide or a membrane-spanning region.
Gene: Protein-coding gene on chromosome 5 (76,083,383 to 76,353,939, forward strand). Ensembl gene ENSG00000122012.
Subcellular location: Cytoplasmic vesicle, secretory vesicle, synaptic vesicle membrane
Subcellular location (Human Protein Atlas): Nucleoplasm; Vesicles
Pathways (Reactome):
Disease: Toxicity of botulinum toxin type A (botA); Toxicity of botulinum toxin type D (botD); Toxicity of botulinum toxin type F (botF)
Gene Ontology:
Molecular function: protein binding; transmembrane transporter activity
Biological process: regulation of synaptic vesicle exocytosis; chemical synaptic transmission; transmembrane transport
Cellular component: nucleoplasm; plasma membrane; synaptic vesicle; synaptic vesicle membrane; dopaminergic synapse; membrane
Genetic constraint (gnomAD): Loss-of-function variants: 42 observed, 75.45 expected, observed/expected ratio (o/e) 0.56, 90% interval 0.43 to 0.72. The upper end of that interval is the gene's LOEUF score, 0.72, which puts it in group 2 of 6, group 1 being the genes least tolerant of losing a copy. Missense variants: 816 observed, 937.69 expected, observed/expected ratio (o/e) 0.87, 90% interval 0.82 to 0.92. Synonymous variants: 323 observed, 342.37 expected, observed/expected ratio (o/e) 0.94, 90% interval 0.86 to 1.03.
Homologues: Orthologues: chimpanzee SV2C (99% identical), macaque SV2C (99% identical), mouse Sv2c (97% identical), rat Sv2c (97% identical), guinea pig SV2C (96% identical), pig SV2C (93% identical), dog SV2C (93% identical), rabbit SV2C (91% identical), tropical clawed frog sv2c (83% identical), zebrafish sv2ca (76% identical). Paralogues in human: SV2A (64% identical), SV2B (58% identical).
Diseases named in the same sentence as SV2C in open-access papers:
SV2C is named in the same sentence as 28 diseases in open-access papers, as found by Europe PMC text mining. Sharing a sentence is not in itself a finding about the gene and the disease. The quoted sentences say what the papers report.
Parkinson disease (11 papers, 2017 to 2025). A progressive degenerative disorder of the central nervous system characterized by loss of dopamine producing neurons in the substantia nigra and the presence of Lewy bodies in the substantia nigra and locus coeruleus. "The isoforms SV2A, SV2B and SV2C are implicated in neurological diseases such as epilepsy, Alzheimer's and Parkinson's disease." (PMID 33588752, 2021). "Some studies have evaluated the possible relation between SV2C and Parkinson’s disease, as SV2C modulates dopamine release." (PMID 31052478, 2019). "Recent findings suggest a role of SV2C in the disruption of dopamine signaling in Parkinson’s Disease." (PMID 31887157, 2019). "After 6-hydroxydopamine and MPTP-induced lesions (two experimental models of Parkinson’s diseases), SV2C mRNA levels increased significantly." (PMID 28588450, 2017).
epilepsy (5 papers, 2019 to 2024). A brain disorder characterized by episodes of abnormally increased neuronal discharge resulting in transient episodes of sensory or motor neurological dysfunction, or psychic dysfunction. "Additional research is also needed to determine the mechanism of action of investigational epilepsy drugs targeting SV2C, as they could potentially be repurposed for PD if confirmed as safe and effective activators." (PMID 39711693, 2024). "Clinical trials targeting SV2C are currently ongoing for epilepsy, although it is unclear whether the drug is an activator or inhibitor." (PMID 39711693, 2024). "At several epilepsy-related genes, like HDAC11, SPP1, GAL, DRD1 and SV2C, significant differential methylation and differential gene expression coincided." (PMID 31887157, 2019).
breast carcinoma (3 papers, 2020 to 2025). "Of note, LCN1P1 and SV2C are also expressed in melanoma and other cancers such as breast cancers, respectively." (PMID 41026527, 2025). "We screened out five protein coding genes (EDN2, CLEC3B, SV2C, WT1, and MUC2) significantly corresponding to the overall survival time of patients with breast cancer in the training group." (PMID 34513664, 2021). "Of the five biomarkers, three genes (EDN2, WT1, and MUC2) were upregulated in the breast cancer samples while CLEC3B and SV2C were decreased." (PMID 34513664, 2021). "According to the results, EDN2, CLEC3B, SV2C, and WT1 could significantly influence the prognosis of breast cancer patients." (PMID 34513664, 2021).
memory impairment (2 papers, 2021). "Collectively, our study demonstrates that miR-96 negatively regulates the expression of SV2C, which consequently leads to depression-like behavior and memory impairment in mice." (PMID 33815074, 2021). "Our data indicated that the expression of miR-96 was increased, whereas that of SV2C was decreased in the CA1 region of mice exhibiting depression-like behavior and memory impairment." (PMID 33815074, 2021).
neuroblastoma (2 papers, 2013 to 2021). Neuroblastoma (NB) is the most common solid, extracranial childhood tumor. "Human neuroblastoma SH-SY5Y cells were also evaluated in the SPR binding assay because they have low sensitivity to BoNT/A and express very little endogenous SV2C." (PMID 23696738, 2013).
autism (1 paper, 2018). Persistent deficits in social interaction and communication and interaction as well as a markedly restricted repertoire of activity and interest as well as repetitive patterns of behavior. "Notably, these included transcripts for adhesion proteins such as CDH13, CDH9, CDH15 and SLITRKs, all strongly linked to ASD, presynaptic molecules such as SYNIII and SV2C, associated with non-syndromic autism and SCZ, and post-synaptic transcripts such as DLGAP2 and GRIN2D, linked to SCZ." (PMID 30185603, 2018).
cognitive decline (1 paper, 2021). "Furthermore, GAP43 and SV2C, synaptic markers of cognitive decline in the brains of dementia patients, were revealed here to interact with CaMKIId and were decreased in the hippocampus of FD mice." (PMID 34758889, 2021).
glioma (1 paper, 2020). A benign or malignant brain and spinal cord tumor that arises from glial cells (astrocytes, oligodendrocytes, ependymal cells). "Only a few members of the SV2 protein family, such as SV2B and SV2C, have been found to be differentially expressed in glioma grade II." (PMID 32667033, 2020).
prostate small cell carcinoma (1 paper, 2019). A neuroendocrine carcinoma of the prostate gland with unfavorable prognosis, composed of small cells containing neurosecretory granules. "In contrast, the SV2B isoform is related with prostate small cell carcinoma and the SV2C isoform is generally associated with the correct functioning of basal ganglia nuclei." (PMID 31052478, 2019).
schizophrenia (1 paper, 2024). A major psychotic disorder characterized by abnormalities in the perception or expression of reality. "Here, we report the increased expression of SYP and another gene related to synaptic function (SV2C) in female schizophrenia patients." (PMID 39068467, 2024).
tumor (4 papers, 2021 to 2026). "However, TCF7L1, SCG3 and SV2C were the specifically expressed genes of tumor cell subtypes in primary tumor sites." (PMID 35494058, 2022). "By contrast, SV2C seemed to play a key role as a tumor suppressor in the EMT signaling pathway." (PMID 34513664, 2021). "In addition, SV2B expression was substantially higher than that of SV2A and SV2C in TFE3‐RCC tissues, suggesting that padsevonil inhibited tumor progression in TFE3‐RCC primarily by targeting SV2B." (PMID 41199339, 2026). "Compared with tumor cells at the primary site, metastatic tumor cells still retained high expressions of KRT8 and KRT18, whereas metastatic tumor cells no longer expressed MMRN1, PROX1, TCF7L1, SCG3 and SV2C." (PMID 35494058, 2022).
neurodegenerative disease (2 papers, 2021 to 2022). A disorder of the central nervous system characterized by gradual and progressive loss of neural tissue and neurologic function. "Finally, several proteins that are associated with neurodegenerative diseases were upregulated either during isolation (Pfn4, C1qb, Bag5 and Sv2c) or following regrouping (oxidative phosphorylation-associated genes such as Ndufc2)." (PMID 34650208, 2022).
SV2C also shares sentences with these, for which no sentence is quoted: cancer (1 paper); Cognitive impairment (1); dementia (1); depression (1); gastric cancer (1); gestational diabetes mellitus (1); HIV-1 infection (1); infection (1); melanoma (1); migraine (1); neurological diseases (1); preeclampsia (1); seminoma (1); status epilepticus (1); testicular seminoma (1); virus infection (1).